IDH1 (isocitrate dehydrogenase (NADP(+)) 1)
Diseases named in the same sentence as IDH1 in open-access papers (continued):
Sharing a sentence is not in itself a finding about the gene and the disease.
glioma (continued). "The findings of our research demonstrated a significant elevation of LINC00475 in IDH1 wild-type gliomas compared to IDH1-mutant gliomas, thereby corroborating a positive correlation between high LINC00475 levels and poor outcome in glioma patients." (PMID 38405130, 2024). "IDH1 mutations occur in over 70% of LGG and GBM that progress from LGG and IDH2 mutation occur in less than 5% in gliomas." (PMID 39208202, 2024). "Mutations in the IDH1 and IDH2 genes are commonly found in certain types of tumors (particularly in brain tumors known as gliomas) and result in the production of an oncometabolite called 2-hydroxyglutarate (2-HG)." (PMID 39170262, 2024). "A greater number of genes were upregulated than downregulated with VPA treatment in both IDH1 WT and IDH1 MT glioma cell lines." (PMID 39149696, 2024). "Indeed, mutated IDH1 transforms isocitrate into D-2-hydroxy-ketoglutarate (D2-HG), which inhibits the dioxygenase activity of TETs, leading to an accumulation of methylated cytosine residues and the occurrence of the so-called glioma hypermethylator phenotype (G-CIMP)." (PMID 39595195, 2024). "Ivosidenib is an IDH1 inhibitor that has been approved for acute myeloid leukemia and cholangiocarcinomas and is being investigated in IDH-mutated gliomas, among other tumors." (PMID 39000083, 2024). "In WHO grade III astrocytomas with the R132H mutation in IDH1, OCT4 expression levels were on average higher than in wild-type gliomas and were associated with a worse patient prognosis." (PMID 38392188, 2024). "IDH mutant glioma tissue and brain tumor stem cells derived from IDH1 mutant glioma tissue show reduced expression of lactate dehydrogenase A (LDHA), the enzyme responsible for converting pyruvate into lactate." (PMID 39596840, 2024). "The mutant IDH enzymes, particularly the IDH1 R132H and the IDH2 R172 variants, have been extensively studied in lower- and higher-grade gliomas." (PMID 39201639, 2024). "MRK-A offers significant survival benefits in vivo, despite having minimal effect on IDH1-mutant glioma cell proliferation in vitro." (PMID 38660136, 2024). "Although the prior work did not investigate lipid droplets, we found an increase in lipid droplets in the IDH1 MT glioma cell line with both VPA and oleic acid treatment." (PMID 39149696, 2024). "Our analysis showed a change in FASN mRNA expression only with HDAC6 knockdown in IDH1 MT glioma cell line HK252." (PMID 39149696, 2024). "In our study, we found that IDH1 MT gliomas are more sensitive to VPA when compared to IDH1 WT glioma cell lines." (PMID 39149696, 2024). "Mutations in the IDH1 and IDH2 genes strongly correlate with the development of glioma, acute myeloid leukemia, chondrosarcoma, intrahepatic cholangiocarcinoma, and angioimmunoblastic carcinomas of T-cell lymphomas." (PMID 38674026, 2024). "Perhaps VPA’s pleiotropic targets are more of an advantage than a disadvantage for the treatment of IDH1 MT gliomas." (PMID 39149696, 2024). "IDH1-mutant gliomas preferentially affect young and middle-aged adults and are associated with major morbidity and mortality due to a lack of curative treatments." (PMID 39605316, 2024). "Extracted DNA from two FFPE glioma samples, IDH1 p.R132H with VAF of 39.5% and IDH2 p.R172K with VAF 48.9% (Sample 22), were diluted with DNA extracted from IDH1/2 wild-type FFPE glioma sample." (PMID 38796421, 2024). "This lays the groundwork for the development and utilization of several targeted IDH1/2 inhibitors in the treatment of IDH‐mutant glioma and other IDH‐mutant tumors." (PMID 38339779, 2024). "According to recent clinical trial results (NCT04164901), vorasidenib’s ability to penetrate the brain and target mutations in IDH1 and IDH2 enzymes showed significantly improved PFS in patients with grade 2 glioma." (PMID 38539537, 2024). "B7-H3 is upregulated in IDH1-WT gliomas within the immune checkpoint family, particularly in the mesenchymal subtype." (PMID 38720342, 2024).
glioma (continued). "IDH1 is expressed in the cytosol and peroxisomes and produces NADPH for fatty acid biosynthesis, with oncogenic mutations commonly associated with glioma." (PMID 39596840, 2024). "Results showed significantly higher D-2HG levels in IDH1-mutant gliomas (1.9 mM) compared to wild-type gliomas (70.9 μM)." (PMID 38982076, 2024). "We further observed that high riskscore was associated with malignant characteristics, such as high‐grade glioma, 1p19q non‐codeletion, IDH1 wildtype." (PMID 39620895, 2024). "In the X vs. All test, the well-known hotspot IDH1-132 in gliomas demonstrated a clear difference in survival curves, with 384 patients carrying the mutation compared to 115 patients without it." (PMID 38473427, 2024). "Ivosidenib is a specific, reversible, allosteric competitive inhibitor of mutant IDH1, and has shown clinical utility in treating IDH1-mutant gliomas." (PMID 39596840, 2024). "This suggests that IDH1 MT glioma cell lines perhaps increase cholesterol biosynthesis as a compensation for FASN inhibition." (PMID 39149696, 2024). "Research by Kesler and colleagues found that less invasive IDH1 mutant gliomas had significantly higher global efficiency in brain networks than wild-type tumors." (PMID 39135733, 2024). "In a phase 1b/2 trial enrolling 26 adult patients with relapsed/refractory WHO Grade 3 and 4 IDH1 R132X-mutant glioma, olutasidenib resulted in a disease control rate (objective response plus stable disease) of 48%." (PMID 39876890, 2024). "According to the results of Gene Ontology (GO) analysis, Kaplan–Meier (K-M) survival analysis, and Pearson correlation analysis, CD163 expression is positively correlated with the malignancy of gliomas, especially in IDH1-WT GBM and mesenchymal subtypes." (PMID 38720342, 2024). "More recently, the dual IDH1/IDH2 inhibitor vorasidenib has been approved for the treatment of IDH-mutant glioma following surgery." (PMID 39409901, 2024). "Mutations in the genes encoding IDH1 and IDH2 and, less commonly, IDH3 have been found in a variety of cancers, most commonly glioma, acute myeloid leukemia (AML), chondrosarcoma, and intrahepatic cholangiocarcinoma." (PMID 39000443, 2024). "In conclusion, our preclinical evaluation demonstrated a target-specific internalization of [18F]AG-120 in vitro, a high metabolic stability in vivo in mice, and a slightly higher accumulation of activity in IDH1R132H-glioma compared to IDH1-glioma." (PMID 37982850, 2024). "2-HG is catalyzed from α-ketoglutarate by a mutant IDH1 such as the one found in grade 2 and 3 gliomas and is, therefore, termed an “oncometabolite”." (PMID 39518074, 2024). "Our results present evidence supporting a significantly better prognosis, TMZ treatment efficacy, and higher D-2HG level in IDH1-mutant gliomas compared to their IDH1 wild-type counterparts." (PMID 38982076, 2024). "There are various studies using different IHC markers for the stratification of glial tumors, but the two most common markers that form baseline investigations are IDH1 and ATRX." (PMID 39192927, 2024). "Among gliomas with ATRX loss, 89% retained IDH1/2 mutations while ATRX retention in IDH1/2 mutants was strongly associated with 1p/19q loss, making this a differentiating feature associated with oligodendroglioma." (PMID 39596840, 2024). "The IDH1 WT cell lines tested were more sensitive to belinostat than IDH1 MT glioma cell lines (WTIC50 = 0.84; MTIC50 = 1.97)." (PMID 39149696, 2024).
glioma (continued). "IHC results indicated that the positive rate for IDH1 R123H in 125 glioma cases was 49.6% (62/125), while qPCR and first-generation sequencing showed that the mutation rate of the IDH1/2 gene was 46.4% (58/125)." (PMID 38404571, 2024). "We tested three different HDACis, VPA, panobinostat, and belinostat in varying concentrations in IDH1 WT and IDH1 MT primary glioma cell lines." (PMID 39149696, 2024). "The INDIGO trial, a phase 3 study involving 331 patients with residual or recurrent grade 2 IDH-mutant gliomas, demonstrated the efficacy of vorasidenib, an oral, brain-penetrant inhibitor of mutant IDH1 and IDH2." (PMID 39439623, 2024). "In a mouse glioma model, treatment with mutant IDH1 reduced levels of the chemokine CXCL10 and inhibited T cell aggregation at the tumor site." (PMID 38581001, 2024). "As expected, U87MG glioma cells expressing the IDH1-R132H mutant and patient-derived xenografts from IDH1 mutant GBM both showed lower cellular NADPH levels and a decreased [NADPH]/[NADP+] ratio." (PMID 39596840, 2024). "In clinical samples from human patients with IDH1 mutant gliomas, it was found that CD8+ T cells take up tumor-derived D-2HG, which changes their metabolic program." (PMID 38216787, 2024). "The two most studied drugs in glioma are Ivosidenib (AG-120), a mutant IDH1 inhibitor, and Vorasidenib (AG-881) an IDH1/2 inhibitor." (PMID 39596840, 2024). "Concerning the spectrum of IDH-mutant gliomas, diagnosis of an IDH-mutant astrocytoma requires histopathological findings consistent with an infiltrating diffuse glioma with an IDH1/IDH2 mutation and ATRX loss/mutation or exclusion of 1p/19q codeletion." (PMID 37658995, 2024). "The biosynthesis of fatty acids, membrane lipids and cholesterol is perturbed in IDH1 mutant glioma." (PMID 39596840, 2024). "IDH1 status is an important molecular feature of glioma, with wild-type IDH frequently found in primary GBMs, while IDH mutations are observed in GBMs arising from LGGs." (PMID 38560572, 2024). "We performed either DMSO (vehicle) or RSL3 treatments for 18 h on organotypic slice cultures from six gliomas, including five primary GBMs and an IDH1-mutant anaplastic astrocytoma (Table EV2)." (PMID 39192032, 2024). "Ivosidenib, IDH1/2 inhibitors, had a higher median PFS of 13.6 months for recurrent IDH‐mutated high‐grade gliomas." (PMID 39118481, 2024). "The mutant enzymes, in particular, the IDH1 R132H and IDH2 R172K variants, have been widely studied in low- and high-grade gliomas." (PMID 39457600, 2024). "IDH1-mutant gliomas manifest the cytosine-phosphate-guanine (CpG) island methylator phenotype (G-CIMP+)." (PMID 38957232, 2024). "We collected basic information from 182 IDH1 wild-type and 339 IDH1-mutant glioma patients in our hospital and analyzed various prognostic factors." (PMID 38982076, 2024). "These tumors revealed characteristic histopathological findings of high-grade glioma or glioblastoma and harbored wild-type IDH1/2 according to whole exome sequencing (WES)." (PMID 38605367, 2024). "Consistent with its role as an HDACi, VPA increased histone acetylation and transcriptionally activated many more genes compared to downregulated genes in both IDH1 WT and MT glioma cell lines." (PMID 39149696, 2024). "Compared with the pedHGG_H3-/IDH-wt subtype (median OS: 15.2 months [Q1–Q3: 10.9–23.7]), IDH1-mutant gliomas showed prolonged survival (median OS: 54.6 months [Q1–Q3: 27.7–131.2]), whereas the number of cases is too small to draw a statistical conclusion." (PMID 38717379, 2024). "We then assess D-2HG levels and its anti-glioma efficacy to determine the differences between IDH1-mutant and wild-type gliomas." (PMID 38982076, 2024). "In glioblastoma, various in vitro drug screening studies have identified OMA as a potent anti-glioma agent in both isocitrate dehydrogenase (IDH1) wildtype and mutant tumors." (PMID 39770529, 2024).
glioma (continued). "The most common and aggressive type of these gliomas is called glioblastomas (glioblastomas IDH1-wtGrade 4, 2021 World Health Organization Classification of Tumors of the Central Nervous)." (PMID 40093343, 2024). "Several biomarkers, such as the isocitrate dehydrogenase mutation (IDH-1), alpha-thalassemia/mental retardation, and the X-linked mutation (ATRX), enable more accurate glioma classification and facilitate patient management." (PMID 38633919, 2024). "Over 80% of grades 2 and 3 gliomas carry IDH mutations, often IDH1 gain-of-function mutations, which prevent the formation of hydrogen bonds with the alpha and beta carboxyl sites in isocitrate and disrupt metabolic processes." (PMID 39594997, 2024). "To determine if ATRX mutations associate with inflammatory signaling pathways in glioma patients, we first performed gene set enrichment analysis (GSEA) on TCGA bulk RNAseq data from IDH1-mutant low-grade gliomas (LGG)." (PMID 38272925, 2024). "Gliomas are more sensitive to temozolomide chemotherapy due to MGMT gene methylation, which is driven by mutations in the IDH1 gene." (PMID 39768176, 2024). "This further suggests that while VPA targets FASN, the net metabolic effect of VPA and TVB-2640 on the lipidome is distinct in the IDH1 MT glioma cell line and it is different when compared to the IDH1 WT cell line HK157." (PMID 39149696, 2024). "That is, R132H mutation, which disrupts normal function of isocitrate dehydrogenase IDH1, negatively affects the growth of glioma progenitor cells, but genetically induced expression of human GLUD2 but not GLUD1 rescues the cells." (PMID 38673928, 2024). "The migratory activity of glioma cells in vivo with the IDH1 R132H/wt genotype is regulated by high levels of HA and CS in the tumor, while cells with low migratory potential are apparently selected." (PMID 39596246, 2024). "Binary logistic regression analyses were performed to differentiate between high-grade (HGG) vs. low-grade gliomas (LGG), IDH1/2 wildtype vs. mutated gliomas, and high-grade astrocytic tumors vs. high-grade oligodendrogliomas." (PMID 39123372, 2024). "For example, adult gliomas are often driven by IDH1 or IDH2 mutations, while subsets of low-grade pediatric gliomas are driven by rearrangements in the transcription factor-encoding proto-oncogenes MYB or MYB like 1 (MYBL1)." (PMID 38353122, 2024). "Having IDH1 or IDH2 mutations is associated with improved survival as these gliomas respond better to temozolomide therapy." (PMID 39200342, 2024). "To further explore the role of Itgb4 in gliomas, we analyzed the relationship between Itgb4 expression and IDH1 status in both CGGA and TCGA databases." (PMID 38982076, 2024). "We found in both IDH1 WT and IDH1 MT primary glioma cell lines, GO terms related to cell cycle and DNA repair were downregulated, whereas GO terms related to neurogenesis were upregulated after VPA treatment." (PMID 39149696, 2024). "We further find that HDACs are involved in the regulation of lipogenic genes and HDAC6 is particularly important for the regulation of FASN in IDH1 MT glioma." (PMID 39149696, 2024). "Wild‐type IDH1 regulates the migration of primary glioma cells by catalyzing the production of α‐KG, which mediates the activation of the PI3K/AKT/mTOR pathway cascade phosphorylation." (PMID 39584783, 2024). "A randomized trial in patients with recurrent high-grade glioma demonstrated the independent prognostic significance of IDH1/2 and MGMT methylation status for prolonged OS." (PMID 39049072, 2024). "In summary, our study, drawing from clinical data of over 2500 glioma patients, confirms the superior prognosis of IDH1-mutant glioma patients compared to those with IDH1 wild type, coupled with their heightened sensitivity to TMZ." (PMID 38982076, 2024). "They compared the DTI-ALPS index in patients with different stages of glioma, the type of isocitrate dehydrogenase 1 (IDH1), and the sex of the patients." (PMID 38819694, 2024).
glioma (continued). "Missense mutations in the gene isocitrate dehydrogenase one (IDH1) reprogram the metabolic and epigenetic landscape of IDH1 mutant (MT) gliomas making them molecularly and physiologically distinct from IDH1 wildtype (WT) gliomas." (PMID 39149696, 2024). "In recent years, mutated IDH1 and MGMT promoter methylation were the most common research targets in gliomas and they were associated with longer OS and PFS." (PMID 39049072, 2024). "Given glioma histology, GLISP prediction of IDH1/2 mutation is diagnostically and prognostically important." (PMID 39851286, 2024). "TAM heterogeneity is influenced by genetic alterations in glioma cells, such as mutations in genes like NF1, PTEN, and IDH1." (PMID 39409893, 2024). "Based on the increased 2HG levels in the IDH1R132H-mutant tumors as well as the transcriptomic data, we wanted to examine if H3K27me3 levels differed between IDH1 mutant and wild-type mouse glioma cells." (PMID 38334611, 2024). "Around 80% of grade II and III astrocytomas, oligodendrogliomas, secondary GBM, and tumors that develop from lower-grade gliomas exhibit alterations in the genes responsible for IDH1 or, less frequently, IDH2." (PMID 38686271, 2024). "Consistently, these AS score–correlated RBPs are also differentially expressed between mutant IDH1- and EGFRvIII-driven iPSC glioma models." (PMID 38662454, 2024). "Regarding the IDH status in thalamic tumors, current studies indicate that mutations in the IDH1 and IDH2 genes are relatively uncommon in thalamic gliomas compared to their prevalence in gliomas located in other regions, such as the frontal lobe." (PMID 39459454, 2024). "In fact, the knockdown of some HDACs in the IDH1 MT glioma cell line HK252 actually upregulated many lipogenic enzymes such as SCD and HMGCR." (PMID 39149696, 2024). "The accumulation of 2-hydroxyglutarate, mediated by IDH1, plays a crucial role in glioma progression, rendering IDH1 an important marker for molecular typing of glioma." (PMID 38405130, 2024). "IDH1-WT gliomas, which grow faster, worsen neurocognitive function compared with IDH1-Mut gliomas, despite similar tumour size." (PMID 39598176, 2024). "We characterized the effect of VPA on the overall chromatin architecture of IDH1 MT gliomas and showed that VPA alters promoter accessibility and inhibits transcription of several lipogenic enzymes, including FASN, in IDH1 MT gliomas." (PMID 39149696, 2024). "Small molecule inhibitors of mutant IDH1/2 enzymes have shown promising results in IDH-mutant gliomas." (PMID 39360264, 2024). "Previous observations indicate similar clinical characteristics and progression patterns of IDH1/2-mutant glioma in pediatric and adolescent patients compared to those in adults." (PMID 39056798, 2024). "Previous studies have established that gliomas carrying the IDH1 mutant (IDH1R132H) exhibited antiproliferative characteristics due to hypermethylation of DNA and chromatin." (PMID 38326807, 2024). "Another study later corroborated that high CCT6A levels in glioma correlate with elevated WHO grade, fewer IDH1/2 mutations and shorter overall survival." (PMID 38212481, 2024).